PGLYRP1 (peptidoglycan recognition protein 1)
Description:
Innate immunity protein that plays several important functions in antimicrobial and antitumor defense systems. Acts as a pattern receptor that binds to murein peptidoglycans (PGN) of Gram-positive bacteria and thus provides bactericidal activity. Forms an equimolar complex with heat shock protein HSPA1A and induces programmed cell death through apoptosis and necroptosis in tumor cell lines by activating the TNFR1 receptor on the target cell membrane. In addition, acts in complex with the Ca(2+)-binding protein S100A4 as a chemoattractant able to induce lymphocyte movement. Mechanistically, this complex acts as a ligand of the chemotactic receptors CCR5 and CXCR3 which are present on the cells of the immune system. Also promotes the activation of lymphocytes that become able to kill virus-infected cells as well as tumor cells by modulating the spectrum of their target-cell specificity. Induction of cytotoxicity on monocyte surface requires interaction with TREM1 receptor.
Synonyms: PGRP-S; PGLYRP; PGRP; TNFSF3L; TAG7; PGRPS
Tractability: Antibody: UniProt places it where antibodies can reach, with high confidence; its Gene Ontology location is reachable by antibodies, with high confidence; UniProt predicts a signal peptide or a membrane-spanning region.
Gene: Protein-coding gene on chromosome 19 (46,019,153 to 46,023,053, reverse strand). Ensembl gene ENSG00000008438.
Subcellular location: Secreted; Cytoplasmic granule
Subcellular location (Human Protein Atlas): Vesicles; Cytosol; Nucleoplasm; Predicted to be secreted
Pathways (Reactome):
Immune System: Antimicrobial peptides; Neutrophil degranulation
Gene Ontology:
Molecular function: Hsp70 protein binding; molecular adaptor activity; peptidoglycan binding; peptidoglycan immune receptor activity; receptor ligand activity; N-acetylmuramoyl-L-alanine amidase activity; zinc ion binding
Biological process: antimicrobial humoral immune response mediated by antimicrobial peptide; defense response to Gram-positive bacterium; detection of bacterium; killing of cells of another organism; immune response; innate immune response; peptidoglycan catabolic process; signal transduction
Cellular component: extracellular exosome; extracellular region; phagocytic vesicle lumen; specific granule lumen; tertiary granule lumen
Genetic constraint (gnomAD): Loss-of-function variants: 18 observed, 18.72 expected, observed/expected ratio (o/e) 0.96, 90% interval 0.66 to 1.42. The upper end of that interval is the gene's LOEUF score, 1.42, which puts it in group 5 of 6, group 1 being the genes least tolerant of losing a copy. Missense variants: 261 observed, 276.4 expected, observed/expected ratio (o/e) 0.94, 90% interval 0.85 to 1.05. Synonymous variants: 89 observed, 108.95 expected, observed/expected ratio (o/e) 0.82, 90% interval 0.69 to 0.97.
Homologues: Orthologues: chimpanzee PGLYRP1 (96% identical), macaque PGLYRP1 (85% identical), rabbit PGLYRP1 (72% identical), pig PGLYRP1 (69% identical), mouse Pglyrp1 (64% identical), dog PGLYRP1 (63% identical), guinea pig PGLYRP1 (63% identical), rat Pglyrp1 (63% identical), tropical clawed frog pglyrp1l (46% identical), Drosophila melanogaster PGRP-SC1a (43% identical), Drosophila melanogaster PGRP-SC1b (43% identical), Drosophila melanogaster PGRP-SC2 (42% identical), and 9 more. Paralogues in human: PGLYRP4 (40% identical), PGLYRP3 (40% identical), PGLYRP2 (37% identical).
Diseases named in the same sentence as PGLYRP1 in open-access papers:
PGLYRP1 is named in the same sentence as 92 diseases in open-access papers, as found by Europe PMC text mining. Sharing a sentence is not in itself a finding about the gene and the disease. The quoted sentences say what the papers report.
Arthritis (6 papers, 2009 to 2024). Inflammation of a joint. "In arthritis, PGLYRP1 exerts anti-inflammatory effects by reducing the levels of pro-inflammatory cytokines and chemokines in the blood." (PMID 39687011, 2024). "The anti-inflammatory function of PGLYRP-1 manifests itself only in the later stages of MDP-induced arthritis, which is consistent with the local release of PGLYRP-1 from PMN granules after PMNs' arrival into the mice foot." (PMID 19710928, 2009). "The main focus of this work was to study cytokines released in CFA-induced arthritis in ICR mice as well as the regulation of blood levels of cytokines by two peptides of the innate immunity protein Tag7 (PGLYRP1) capable of blocking the activation of the TNFR1 receptor." (PMID 36293292, 2022). "Pglyrp1 has a pro-inflammatory effect in three mouse models of inflammatory skin diseases (psoriasis, atopic dermatitis, and contact dermatitis) and in experimentally induced asthma, but has anti-inflammatory effect in experimentally induced arthritis." (PMID 26727498, 2016). "Moreover, PGLYRP-1−/− mice have longer-lasting MDP-induced arthritis than WT mice." (PMID 19710928, 2009). "However, the role of PGLYRP-2 in arthritis is unique because other mouse PGLYRPs, including PGLYRP-1, -3 and -4, do not have similar pro-inflammatory effects." (PMID 27991595, 2016).
asthma (6 papers, 2016 to 2024). "To further investigate how these findings are related to pediatric asthma, we chose to compare PGLYRP-1, sIL6Rα, and their associations with asthma and lung function outcomes." (PMID 33565964, 2021). "The abundance of PGLYRP-1 was significantly associated with current asthma at mid-childhood (adjusted odds ratio [OR] [95% CI]: 0.50 [0.31, 0.77] per 1 SD increase, p-value=0.003)." (PMID 33565964, 2021). "Further validation demonstrated that umbilical cord blood serum concentration of PGLYRP-1, a specific granule protein, was inversely associated with mid-childhood current asthma and early-teen FEV1/FVCx100." (PMID 33565964, 2021). "A soluble specific granule protein, PGLYRP-1, was strongly associated with odds of asthma in childhood and pulmonary function in childhood and adolescence." (PMID 33565964, 2021). "Whether PGLYRP-1 has a causal role in asthma pathogenesis or is merely a biomarker for risk remains to be determined." (PMID 33565964, 2021). "Thus, if perinatal neutrophil abundance is associated with pediatric asthma, both PGLYRP-1 and sIL6Rα should demonstrate associations with these outcomes." (PMID 33565964, 2021). "PGLYRP1 is highly expressed predominantly in neutrophils’ and eosinophils’ granules and its expression was associated with various inflammatory conditions, including atherosclerotic disease, acute myocardial infarction, rheumatoid arthritis, asthma, oral inflammation, and cancer." (PMID 39273682, 2024). "Accumulating evidence shows that ITGB4, SEMA3D, FCAR (Fc fragment of IgA receptor), KIT (KIT proto-oncogene, receptor tyrosine kinase), PGLYRP1, IL17RB, BIRC5 and PTGS1 are associated with prognosis in asthma." (PMID 36837510, 2023). "Peptidoglycan recognition protein 1 (PGLYRP1), an innate proinflammatory and antibacterial protein, has been linked with asthma in animal models, with PGLYRP1-deficient mice exhibiting a decreased Th2/CD4+ response, with a less severe phenotype." (PMID 37474963, 2023). "Increased umbilical cord blood serum PGLYRP-1 is associated with increased FEV1/FVC and reduced odds of pediatric asthma." (PMID 33565964, 2021). "PGLYRP1 has been shown to modulate inflammation in multiple murine models for experimental colitis, asthma, and contact dermatitis." (PMID 33175909, 2020). "Further investigation will be needed to elucidate the role of PGLYRP-1 in adolescent asthma." (PMID 33565964, 2021). "In contrast, we observed a significant relationship between mid-childhood asthma and PGLYRP-1, not sIL6Rα." (PMID 33565964, 2021).
atherosclerosis (6 papers, 2018 to 2022). A disease characterized by the build-up of fatty material and calcium deposition in the arterial wall resulting in partial or complete occlusion of the arterial lumen. "We believed in CVD, PGLYRP-1 alone or linked to PG is the putative ligand of TREM-1 implicated in atherosclerosis." (PMID 30205488, 2018). "PGLYRP1 is also involved in inflammation and associated with atherosclerosis." (PMID 35858774, 2022). "Our results verified that CAMP, LYZ, and PGLYRP1 were important factors in constituting the atherosclerosis of CHD." (PMID 34692829, 2021). "PGLYRP1 was a bacterial wall component known to be present in human atherosclerosis and was found almost exclusively in the secretory granules of neutrophils and eosinophils." (PMID 34692829, 2021). "Throughout the progression of atherosclerosis, PGLYRP1 is expressed in macrophages within atherosclerotic lesions, and its plasma level may reflect inflammation state due to chronic infection." (PMID 32157804, 2020).
mastitis (5 papers, 2013 to 2025). Inflammation of breast tissue during lactation or postpartum due to an obstructed duct or infection. "Additionally, gene polymorphisms in peptidoglycan recognition protein 1 have been linked to mastitis resistance." (PMID 40075958, 2025). "Of these, the antimicrobial peptides CATHL2 and PGLYRP1 were also found to be upregulated in Holstein-Friesian cows with clinical mastitis." (PMID 40315186, 2025). "Considering its important role in immunity and inflammation, PGLYRP1 has been widely targeted in bovine mastitis research." (PMID 36911690, 2023). "When mastitic cows were compared to healthy cows by sampling point, PGLYRP1 remained upregulated with notable log fold-changes from the onset of mastitis (4.31 ±1.55) through to sample 2 (2.15 ±1.06)." (PMID 33195534, 2020). "Of the four genes (C5AR1, CATHL6, LCN2, and PGLYRP1) with evidence of upregulation in cows with mastitis, three of those genes (CATHL6, LCN2, and PGLYRP1) were investigated due to their previously identified association with postpartum disease." (PMID 33195534, 2020). "A higher expression of PGLYRP1 has been documented in cows with mastitis." (PMID 36911690, 2023). "Three genes (PGLYRP1, CATHL6, and LCN2) were differentially expressed between sampling points for mastitic cows when comparing samples from the onset of mastitis to those from sampling points 2 or 3 (B-Y p ≤ 0.05)." (PMID 33195534, 2020). "It is worth acknowledging that a less conservative estimate (uncorrected p ≤ 0.05) indicated upregulation of one other candidate gene (C5AR1) at the onset of mastitis, and ongoing upregulation of LCN2 and PGLYRP1 at sampling points 2 and 3, respectively." (PMID 33195534, 2020). "We identified three genes (CATHL6, LCN2, and PGLYRP1) that were upregulated during the early stages of mastitis regardless of differences in breeds, parities, days in milk, production levels and pregnancy status." (PMID 33195534, 2020). "In confirmation of our hypothesis, PGLYRP1 was expressed differentially in peripheral leukocytes from dairy cows with and without moderate to severe mastitis during the post-voluntary waiting period (B-Y p ≤ 0.05)." (PMID 33195534, 2020).
periodontitis (5 papers, 2020 to 2025). An acute or chronic inflammatory process that affects the tissues that surround and support the teeth. "Investigate whether serum levels of TREM‐1 and PGLYRP1 are associated with periodontitis in patients with RA." (PMID 39811802, 2025). "In RA, periodontitis was associated with increased TREM-1 and PGLYRP1 levels (p < 0.05), yet in patients under methotrexate TREM-1 levels were lower." (PMID 33536478, 2021). "The present study aimed to investigate potential associations that exist in RA patients between serum levels of TREM-1, its ligand PGLYRP1, periodontitis and indicators of RA disease activity." (PMID 33536478, 2021). "Both serum TREM-1 and PGLYRP1 levels were increased in RA patients with periodontitis compared to RA patients with healthy periodontium, supporting a potentiating effect of periodontitis towards RA disease activity and inflammation." (PMID 33536478, 2021). "TREM-1 and PGLYRP1 levels in various biofluids are elevated in periodontitis patients compared to periodontally-healthy controls." (PMID 33536478, 2021). "The mediation analyses showed that serum TREM-1 levels were directly mediated by the presence of periodontitis (B = 52.7259, p = 0.0262) and indirectly mediated via PGLYRP1 serum levels in patients with RA (B = 0.1840, p = 0.0005)." (PMID 33536478, 2021). "In contrast, the lowest levels of TREM-1 (111.6 ± 53.6 pg/ml) and PGLYRP1 (86.6 ± 52.3 pg/ml) were observed in MTX-treated patients devoid of periodontitis." (PMID 33536478, 2021). "This study investigated whether serum levels of TREM-1 and PGLYRP1 correlate with periodontitis in rheumatoid arthritis (RA) patients." (PMID 33536478, 2021). "Moreover, periodontitis was shown to affect the levels of PGLYRP1 (B = 178.3033, p = 0.0037)." (PMID 33536478, 2021). "We further analyzed serum levels of TREM-1 and PGLYRP1 in relation to both MTX use and diagnosis of periodontitis." (PMID 33536478, 2021). "In this regard, higher levels of salivary TREM-1 and PGLYRP1 were associated with poorer oral health in chronic kidney disease patients with concomitant periodontitis, and a positive correlation was found between salivary TREM-1 and PGLYRP1 levels." (PMID 33536478, 2021). "Increased serum TREM-1 levels correlated with PGLYRP1, CRP and DAS-28-ESR in RA patients with periodontitis." (PMID 33536478, 2021). "PGLYRP1 functions as a ligand that activates TREM-1 during illness, so the high values of this biomarker indicate that the patient is probably suffering from systematic inflammation due to periodontitis." (PMID 35225864, 2022). "PGLYRP1 levels were elevated in saliva and GCF of patients with periodontitis, and initial periodontal therapy decreased PGLYRP1 levels in these patients with a stronger effect in non-smokers." (PMID 33536478, 2021). "RA patients diagnosed with periodontitis displayed significantly higher TREM-1 and PGLYRP1 levels as compared to patients without periodontitis (TREM-1; p = 0.001 and PGLYRP1; p = 0.037)." (PMID 33536478, 2021). "The highest serum levels of TREM-1 (244.2 ± 119.2 pg/ml) and PGLYRP1 (317.8 ± 390.6 pg/ml) were observed in non-MTX patients affected by periodontitis." (PMID 33536478, 2021). "On an indicative basis, these associations between periodontitis, TREM-1 and PGLYRP1 levels were not significant in HC and BD groups (p > 0.05), although a similar trend could be observed in HC participants." (PMID 33536478, 2021).
rheumatoid arthritis (5 papers, 2021 to 2026). A chronic, systemic autoimmune disorder characterized by inflammation in the synovial membranes and articular surfaces. "Extending this point, there are reported associations between increased serum PGLYRP-1 and systemic inflammatory conditions in adulthood (e.g. rheumatoid arthritis, cardiovascular disease)." (PMID 33565964, 2021). "In serum samples from SLE patients, it has been reported overexpression of Pglyrp1, a member of the family of bacterial peptidoglycan sensor molecules, and also it was associated with other autoimmune diseases like rheumatoid arthritis Besides, SLE severity is associated with Olr1." (PMID 35211864, 2022).
colitis (4 papers, 2019 to 2024). Inflammation of the colon. "Our results show that macrophages expressing PGLYRP-1 are part of immune responses in human colitis and that ligand-dependent PGLYRP-1 signaling promotes mucosal protection in animal model of the disease." (PMID 39483916, 2024). "Taken these data together, GMTriP-K facilitated mucosal recovery in colitis through PGLYRP-1-dependent immune regulation." (PMID 39483916, 2024). "Pretreatment of mice with GMTriP-K prevented the induction of PGLYRP-1 expression that increased 10-fold during TNBS colitis in MLNs suggesting a ligand-receptor feedback loop." (PMID 39483916, 2024). "Upon induction of TNBS colitis, the lamina propria of wildtype mice showed inflammatory cell infiltration with increased recruitment of F4/80 positive macrophages that expressed PGLYRP-1." (PMID 39483916, 2024). "To determine the importance of GMTriP-K detection by PGLYRP-1 in the regulation of intestinal inflammation, we studied hapten induced colitis after administration of trinitrobenzene sulfonic acid (TNBS)." (PMID 39483916, 2024). "Together, these data suggest that GMTriP-K challenge can provide immune protection to TNBS induced colitis and this protection requires PGLYRP-1." (PMID 39483916, 2024). "We found that PGLYRP-1 expression was significantly increased during TNBS induced colitis." (PMID 39483916, 2024). "Importantly, PGLYRP-1 activation by GMTriP-K resulted in innate immune activation and protection of mice from colitis." (PMID 39483916, 2024). "Interestingly, it was reported that PGLYRP-2−/− and PGLYRP-3−/− mice were highly sensitive to DSS-induced colitis than PGLYRP-1−/− and PGLYRP-4−/− mice, which had intermediate or low sensitivity, respectively." (PMID 31416116, 2019). "Notably, PGLYRP-3−/− mice had the most significant changes in their gut microbiota whereas PGLYRP-1−/− and PGLYRP-4−/− mice were less sensitive to colitis and had fewer alterations in the gut microbiota." (PMID 31416116, 2019).
Sepsis (4 papers, 2016 to 2022). Sepsis is defined as life-threatening organ dysfunction caused by a dysregulated host response to infection. "Among the mRNAs related ygiM we verified, VNN1, CEACAM8, and PGLYRP1 were highlighted about sepsis firstly." (PMID 36212144, 2022). "Expression of HP, QSOX1 (HR = 1.129, p > 0.05), and PGLYRP1 (HR = 1.062, p > 0.05) did not have a statistically significant predictive effect on the survival of patients with sepsis." (PMID 35145983, 2022).
ulcerative colitis (3 papers, 2013 to 2024). An inflammatory bowel disease involving the mucosal surface of the large intestine and rectum. "We were able to detect the PGLYRP-1 dependent gene signature that was regulated by GMTriP-K in ulcerative colitis." (PMID 39483916, 2024). "PGLYRP-1 upregulation and its dependent gene expression signatures were induced in both mouse intestinal inflammation and human ulcerative colitis." (PMID 39483916, 2024). "To determine the involvement of PGLYRP-1 in human inflammatory bowel disease we analyzed the expression of PGLYRP-1 in healthy colon and ulcerative colitis (UC) by immunostaining." (PMID 39483916, 2024).
acute myocardial infarction (2 papers, 2021 to 2024). Necrosis of the myocardium, as a result of interruption of the blood supply to the area. "PGLYRP1 (peptidoglycan recognition protein 1) has been associated with cardiovascular risk factors such as diabetes, hypertension, higher concentration of total cholesterol, lower concentration of HDL-C and history of myocardial infarction." (PMID 34745199, 2021).
coronary artery disease (2 papers, 2024 to 2026). "Long-term treatment of mice with recombinant PGLYRP1 was associated with both increased atherogenic lesions and reduced fractional shortening of the left ventricle, suggesting that PGLYRP1 may be a potential biomarker for coronary artery disease and heart failure." (PMID 39273682, 2024).
depression (2 papers, 2011 to 2023). "In contrast to the conventional drug L-thyroxine for curing hypothyroidism, YJT has an efficacy for attenuating systematic inflammatory responses, related with depression in intestinal TLR4 and Nod2/Pglyrp1 signaling pathways." (PMID 37270649, 2023). "These genes included SBNO2, CEACAM5, AKAP1, UBC, ACTB, UBB, and FOS for schizophrenia; SEC24C, PGLYRP1, ARHGAP4, RPL22, SLC6A11, and SYK for bipolar disorder; and SRRT, PARK2, LILRA4, STK17A, IGFBP2, and NF1 for major depression." (PMID 22373040, 2011).